HIF1A (hypoxia inducible factor 1 subunit alpha)
Diseases named in the same sentence as HIF1A in open-access papers (continued):
Sharing a sentence is not in itself a finding about the gene and the disease.
pancreatic cancer (continued). "Further, we recently reported that HIF-1α expression levels in pancreatic cancer are also associated with tumor progression, fibrotic focus, angiogenesis, cell migration, cell invasion and hepatic metastasis." (PMID 27367674, 2016). "The expression level of HIF-1α in pancreatic cancer is linked to tumor progression, angiogenesis, invasion, and metastasis." (PMID 27271610, 2016). "RAGE-deficient mice have impaired oncogenic KRAS-driven pancreatic tumor growth with significant downregulation of the HIF1α signaling pathway." (PMID 25341034, 2014). "Our meta-analysis suggests that the substitution of C to T of HIF-1α gene C1772T polymorphism is a risk factor of cancer, especially for cervical, head and neck cancer, pancreatic cancer and renal cell carcinoma." (PMID 24367595, 2013). "In preceding works we were able to shed light on a strong association of Hif1a expression with survival in pancreatic cancer and soft tissue sarcomas." (PMID 23704979, 2013). "Our meta-analysis suggests that the substitution of C allele with T at HIF-1α gene C1772T polymorphism is a risk factor of cancer, especially for cervical, head and neck cancer, pancreatic cancer and renal cell carcinoma." (PMID 24367595, 2013). "The overexpression of HIF-1α has been reported in numerous human cancers, including colon, brain, breast, gastric, lung, skin, ovarian, prostate, renal and pancreatic carcinoma, and is associated with a poor prognosis and failure of tumor treatment." (PMID 23833638, 2013). "Previous reports have shown that phosphorylated STAT-3 is associated with over-expression of VEGF and HIF-1α in human pancreatic tumors and that inhibition of STAT-3 causes significant reduction in tumor growth and vascularization." (PMID 22016776, 2011). "Similarly, another study claims that SIRT3 is associated with the regulation of pancreatic cancer progression through its modulation of the HIF-1α pathway." (PMID 39682281, 2024). "In addition, HIF-1α expression is associated with the angiogenesis, cell proliferation and metastasis of pancreatic cancer." (PMID 37892091, 2023). "Hif1α might be an important molecular target for pancreatic cancer caused by BPA exposure, and pregnancy is a critical window of susceptibility to BPA exposure." (PMID 37460698, 2023). "In addition, HIF-1α regulates the balance between NF-κB-associated pro- and anti-apoptosis, resulting in the resistance of pancreatic cancer cells to gemcitabine." (PMID 36551540, 2022). "In a study of pancreatic cancer samples, the expression of toll-like receptors (TLRs), a characteristic type of single-pass membrane-spanning receptor expressed in immune cells, was associated with HIF-1α and CAIX." (PMID 35565420, 2022). "Indeed, gemcitabine resistance is associated with EMT and induction of HIF-1α in pancreatic cancer cells, leading to the pharmacologic manipulation of HIF-1α as novel therapeutic approach to overcome resistance." (PMID 34003341, 2021). "Furthermore, it has been shown that HIF-1α expression increases pancreatic cancer cell motility and metastasis and it is associated with a negative prognosis." (PMID 34885243, 2021). "Additionally, miRNAs are implicated in the regulation of HIF-1α on the EMT of pancreatic cancer cells." (PMID 32587480, 2020). "Elevated levels of tumor HIF-1α are associated with decreased pancreatic cancer patient survival." (PMID 29295482, 2017). "Interestingly, we had previously shown that in CAM pancreatic cancer xenografts, augmented tumor vascularization was associated with high expression of HIF-1α in the nuclei." (PMID 26739387, 2016). "Indeed, LSD1 has been shown to physically associate with HIF1α in melanoma inhibitory activity human pancreatic carcinoma MIA PaCa-2 cells and with KLF5 in embryonic stem cells." (PMID 24886859, 2014).
pancreatic cancer (continued). "In addition to regulating the transcriptional activity of STAT3, APE1 also exerts redox control of other transcription factors, which have been implicated in pancreatic cancer (such as HIF-1α and NF-κB)." (PMID 23094050, 2012). "In this study, we investigated the molecular mechanisms by which the neurotransmitter acetylcholine enhances the expression of HIF-1α in pancreatic cancer cells in hypoxia." (PMID 41608625, 2026). "Under hypoxic conditions, acetylcholine induced a concentration-dependent increase in nAChR-α7-mediated HIF-1α expression in pancreatic cancer cells in vitro, leading to enhanced expression of HIF-1α target genes." (PMID 41608625, 2026). "Collectively, our findings reveal a novel mechanism of acetylcholine-induced enhancement of HIF-1α expression involving PDPK1/YAP signaling and highlight the utility of HIF-1α as a therapeutic target in acetylcholine-potentiated pancreatic cancer." (PMID 41608625, 2026). "Collectively, our data unfolds a novel reciprocal regulatory crosstalk between MYB and HIF1α, driving optimal adaptation of pancreatic cancer cells under hypoxia." (PMID 40680814, 2025). "ITGA3 enhances glycolysis to promote pancreatic cancer growth and metastasis by increasing HIF-1α and c-Myc expression in a Col1-dependent autocrine manner." (PMID 40630951, 2025). "This study focuses on the specific role of the HIF-1α/TGF-β1/Smad axis in pancreatic cancer fibrosis, elucidating its mechanism of promoting tumor progression through ECM remodeling." (PMID 40406267, 2025). "Recently, we identified MYB as a novel player in the hypoxic survival of pancreatic cancer cells through its interaction with HIF1α." (PMID 40680814, 2025). "ENST00000480739 suppresses pancreatic cancer by inhibiting HIF-1α expression through the regulation of OS-9 function in the invasion of pancreatic cancer." (PMID 40861273, 2025). "Our previous work demonstrated a significant role of MYB in supporting the hypoxic survival of pancreatic cancer cells through its induced expression and metabolic reprogramming in cooperation with HIF1α." (PMID 40680814, 2025). "Magnetic nanoparticles (MNPs) have demonstrated the ability to modulate HIF-1α activity and affect autophagy in liver and pancreatic cancers." (PMID 40004215, 2025). "Quercetin, found in numerous fruits and vegetables, has demonstrated the ability to reduce HIF-1α protein levels in pancreatic cancer." (PMID 40004215, 2025). "Therapeutic strategies targeting the HIF-1α/TGF-β1 axis hold significant promise in pancreatic cancer, but efficacy and safety require optimization through refined dosing regimens, selective inhibitors, and multi-target combinations." (PMID 40406267, 2025). "Together, these findings highlight the functional significance of reciprocal crosstalk between MYB and HIF1α, providing novel mechanistic insights into pancreatic cancer pathobiology." (PMID 40680814, 2025). "2-Methoxyestradiol (2-ME) destabilizes HIF-1α, leading to a reduction in autophagy induction in pancreatic cancer at concentrations of 1–10 μM." (PMID 40004215, 2025). "Downregulated ENST00000480739 suppresses HIF-1α expression by promoting the transcription of OS-9, thereby contributing to tumor progression in pancreatic cancer." (PMID 40004471, 2025). "Our findings reveal a novel mechanism by which HIF-1α modulates pancreatic cancer ECM via the TGF-β1/Smad axis, offering potential therapeutic strategies to target the dense stromal component of this malignancy." (PMID 40406267, 2025). "Recently, we also revealed a role of MYB in hypoxic survival of pancreatic cancer cells by promoting metabolic reprogramming through interaction with HIF1α, modulating its expression and binding to glycolytic gene promoters." (PMID 40680814, 2025).
pancreatic cancer (continued). "Collectively, these studies revealed the intricate interplay between hypoxia-related circRNAs and HIF-1α, accelerating the deterioration process and influencing the therapeutic response in pancreatic cancer through a myriad of mechanisms." (PMID 40004471, 2025). "Expression of P4HA1 in pancreatic cancer was demonstrated to be dependent on HIF1α and to correlate with hypoxia gene signatures, and glycolysis." (PMID 39966387, 2025). "Relationship between HIF-1α expression and clinicopathological characteristics of pancreatic cancer patients." (PMID 40406267, 2025). "In pancreatic cancer, hypoxia-inducible factor-1α (HIF-1α) inhibits T cell activity via the GPR81/mTOR/HIF-1α/STAT3 pathway." (PMID 40650086, 2025). "EZN-2208, an antisense oligonucleotide directed against HIF-1α, significantly decreases its expression and suppresses autophagy in pancreatic cancer at concentrations ranging from 10 to 100 nM." (PMID 40004215, 2025). "lncRNA NNT‐AS1 is highly expressed in pancreatic cancer by HIF‐1α‐mediated transcription, and m6A‐modified NNT‐AS1 by METTL3‐HuR stabilizes ITGB1." (PMID 40448344, 2025). "The feedback loop between MTA2TR and HIF-1α regulates the proliferation and invasion of pancreatic cancer cells." (PMID 40861273, 2025). "Mechanistically, HIF-1α-induced exosomal circZNF91 is transferred to normoxic pancreatic cancer cells and serves as a ceRNA of miR-23b-3p, thereby relieving the inhibitory effects of miR-23b-3p on Sirtuin1 (SIRT1) expression." (PMID 40004471, 2025). "Knockdown of lncRNA PVT1 resulted in decreased glucose uptake, lactate secretion, intracellular ATP levels, and HIF-1A expression in pancreatic cancer cells." (PMID 40861273, 2025). "Mesoporous silica nanoparticles (MSNs) demonstrate potential in treating breast and pancreatic cancers by regulating HIF-1α activity and facilitating autophagic clearance." (PMID 40004215, 2025). "Hypoxia, through HIF-1α, is known to promote tumor progression and immune evasion, contributing to chemoresistance in pancreatic cancer." (PMID 39796244, 2025). "HIF-1α is generally highly expressed in digestive system tumors such as liver cancer, gastric cancer, colorectal cancer, pancreatic cancer, and gallbladder cancer." (PMID 40563539, 2025). "In pancreatic cancer, the hypoxic microenvironment activates HIF-1α, which binds directly to the HRE1-binding site in the promoter region of lncRNA LINC00460, thereby promoting its transcription." (PMID 40861273, 2025). "In contrast, we also showed that HIF-1a protein oxidation was greatly elevated in human pancreatic cancer tissues, which was positively correlated with PDAC progression and poor prognosis." (PMID 38493183, 2024). "By inhibiting HIF-1α, miR-519c can increase the sensitivity of pancreatic cancer cells to treatment, offering a potential strategy to overcome chemoresistance and enhance the effectiveness of therapies like GEM." (PMID 39479443, 2024). "Overcoming these challenges will be essential for realizing the full clinical potential of anti-HIF-1α siRNA-loaded NPs in treating pancreatic cancer and other hypoxia-driven malignancies." (PMID 39458615, 2024). "Here, we produce and evaluate HA-displaying CS NPs, using a 180 kDa HA, containing siRNA as an approach to achieving specificity in targeting pancreatic tumor, enhance uptake, and delivering siRNA to knockdown HIF-1α." (PMID 39458615, 2024). "This approach presents a promising strategy for addressing hypoxia-driven treatment resistance in pancreatic cancer by downregulating HIF-1α, a key regulator of tumor survival under low oxygen conditions." (PMID 39458615, 2024). "Collectively, the circ_0000977/miR-153/HIF1α/ADAM10 ceRNA network represents a novel mechanism contributing to the hypoxia-mediated immune escape of pancreatic cancer cells." (PMID 39403602, 2024).
pancreatic cancer (continued). "A recent study has demonstrated that administering miR-519c, which exhibits decreased levels in pancreatic cancer, inhibited HIF1-α within gemcitabine-resistant pancreatic cancer cells under hypoxic conditions." (PMID 38338746, 2024). "Curcumin regulates the expression of Beclin1, an important protein that regulates autophagy and cell self-destruction, and inhibits the proliferation of pancreatic cancer cells by inhibiting the hypoxia-inducible factor-1α (HIF-1α)-mediated pathway." (PMID 39062777, 2024). "The results demonstrated that in hypoxic pancreatic cancer cells, curcumin downregulates Beclin1 expression and inhibits HIF-1α-mediated glycolysis, thereby inhibiting pancreatic cancer cell proliferation." (PMID 39062777, 2024). "Our previous studies have demonstrated that MUC1 stabilizes HIF-1α transcription factor in pancreatic cancer and activates downstream signaling." (PMID 38547055, 2024). "Several studies have highlighted the pivotal role of HIF-1α in the development and progression of pancreatic cancer, particularly in promoting treatment resistance." (PMID 39458615, 2024). "We have previously demonstrated that MUC1-mediated stabilization of HIF-1α is critical for metabolic reprogramming in pancreatic cancer cells." (PMID 38547055, 2024). "For instance, within the hypoxic microenvironment of pancreatic cancer, HIF-1α induces resistance to gemcitabine." (PMID 38338746, 2024). "Deletion of HIF-1α resulted in significantly reduced growth of pancreatic cancer cells under hypoxia." (PMID 38547055, 2024). "Recent studies have reported that HIF-1α responsible for lncRNA PVT1-mediated pancreatic cancer enhancing." (PMID 38740637, 2024). "Previous studies have also found that in gemcitabine-resistant pancreatic cancer cell lines, pyrimidine synthesis increases, leading to gemcitabine resistance through the HIF-1α-induced aerobic glycolysis pathway." (PMID 39519347, 2024). "Crosstalk between MUC1 and HIF-1α signaling renders pancreatic cancer resistant to gemcitabine by inducing anabolic glucose metabolism." (PMID 39588377, 2024). "As of this writing, an abundance of research has documented that lncRNAs regulate proliferation and apoptosis in various tumor cells, including pancreatic cancer, by working in concert with HIF-1α to modulate cell survival and apoptosis." (PMID 38521881, 2024). "A study in 2017 demonstrated that HIF-1α causes an increase in the glycolysis pathway and pyrimidine synthesis, which is the mechanism of gemcitabine resistance in pancreatic cancer, and targeting HIF-1α can increase the effectiveness of gemcitabine." (PMID 39588377, 2024). "Regarding gemcitabine resistance, it was reported that HIF1α is stabilized by increased expression of MUC1 in pancreatic cancer." (PMID 38874588, 2024). "Suppression of miR-519d-3p by PVT1 increases the HIF-1α expression, triggers the Wnt/β-catenin signaling pathway, and promotes the growth and proliferation of pancreatic cancer cells." (PMID 38559560, 2024). "As pancreatic cancer is known to be a highly hypoxic tumor, NiCl2 was added to cells in order to stabilize HIF1α and mimic original tumor conditions." (PMID 38425123, 2024). "CTPS is reported to be highly expressed in gemcitabine‐resistant pancreatic cancer cell lines, with its expression modulated by hypoxia‐inducible factor (HIF)‐1α." (PMID 39030877, 2024). "The elevated SIRT1 then stabilizes the hypoxia-inducible factor 1 α (HIF1α) protein through deacetylation, which subsequently promotes glycolytic metabolism and contributes to the chemoresistance observed in pancreatic cancer cells." (PMID 39682281, 2024). "Together, these results found a ALKBH5/HDAC4/HIF1α positive feedback loop for cellular response to hypoxia in pancreatic cancer." (PMID 37149664, 2023). "HIF1A-AS1 post-transcriptionally augmented HIF-1α expression to promote gemcitabine resistance of pancreatic cancer by enhancing glycolysis." (PMID 37840133, 2023).
pancreatic cancer (continued). "HIF1A-AS1 modulated the HIF1a expression in a glycolysis-dependent manner to promote GEM resistance in pancreatic tumor cells." (PMID 37580768, 2023). "Overall, these results indicated that under hypoxic conditions, HIF-1α induced upregulation of linc00460 in pancreatic cancer, and that this required the HRE1 binding site in the promoter of LINC00460." (PMID 37786443, 2023). "On the other hand, ATF4 has recently been shown to enhance transcription of HIF1α in long-term hypoxia in pancreatic cancer, what would explain detection of HIF1α protein in our hypoxia adapted cells." (PMID 37123244, 2023). "HIF-1α drives hypoxia-induced EMT programming in pancreatic cancer cells through interaction with the nuclear factor kappa-light-chain-enhancer of activated B cells (NF-κB) transcriptional complex." (PMID 36902253, 2023). "VMP1-mediated autophagy is induced by gemcitabine through the transcription factor E2F1 in pancreatic cancer cells and by photodynamic therapy through HIF-1α in colon cancer cells." (PMID 37629161, 2023). "In the context of pancreatic cancer, HIF-1α levels are elevated in part due to the desmoplastic stroma and HIF-1α staining and expression strongly associates with PDAC lymph node metastasis, high tumor stage, poor prognosis, and immune evasion." (PMID 37187740, 2023). "For example, lncRNA HIF1A-AS1 induced gemcitabine resistance in patients with pancreatic cancer by upregulating hypoxia-inducible factor-1 alpha (HIF-1α) expression and enhancing glycolysis." (PMID 37981573, 2023). "3-bromopyruvate and the glucose analog 2-Deoxy-D-glucose (2-DG), when used together, have greater anticancer effects in pancreatic cancer cells, as they inhibit glycolysis as well as HIF-1α." (PMID 37460927, 2023). "HIF-1α upregulates VEGF production in pancreatic cancer cells by binding to the hypoxia response element of the VEGF-A promoter upon nuclear translocation." (PMID 37626752, 2023). "Our results showed a reduction in the level of CD31 and HIF-1α protein expression after treatment with 8a, indicating that compound 8a inhibited angiogenesis in pancreatic cancer." (PMID 37888452, 2023). "Downregulation of GPR116 receptor promoted the anti-pancreatic cancer function of NK cells through Gαq/HIF1α/NF-κB signaling pathway." (PMID 36895027, 2023). "Specifically, the HIF-1α gene was down-regulated in the bone marrow as compared to the blood and pancreatic tumors of OT mice." (PMID 36614196, 2023). "The authors studied wild-type (WT) MiaPaCa2 pancreatic cancer cells and a MiaPaCa2 subline transfected with an HIF-1α-specific small interfering (siRNA)." (PMID 37361580, 2023). "Conversely, knockdown of endogenous HDAC4 facilitated HIF1α protein degradation in hypoxic pancreatic cancer cells." (PMID 37149664, 2023). "Our study also confirmed that overexpressing HIF1α promoted ALKBH5 transcription in pancreatic cancer cells." (PMID 37149664, 2023). "Over expression of HIF1α has been observed in different cancers such as gastric pancreatic cancer, NSCLC, thyroid cancer and leukemia." (PMID 36809279, 2023). "MMP-15 (MT2-MMP) is upregulated by HIF-1α under hypoxia conditions (1% oxygen) in pancreatic cancer PANC-1 cells since its transcription is inhibited by HIF-1α siRNA or the YC-1 HIFs’ inhibitor." (PMID 38069210, 2023). "Remarkably, digoxigenin inhibited HIF-1α translation, increasing pancreatic cancer cells’ sensitivity to gemcitabine." (PMID 36776312, 2023). "Previous research indicated that NRP1 was correlated with HIF1α expression in pancreatic cancer and non-small cell lung cancer (NSCLC)." (PMID 36841806, 2023). "We found that neutrophils infiltrate pancreatic tumors in large numbers and that these neutrophils exhibit a pronounced glycolytic signature and express high levels of HIF-1α." (PMID 36614196, 2023).